DHX37 (DEAH-box helicase 37)
Diseases named in the same sentence as DHX37 in open-access papers (continued):
Sharing a sentence is not in itself a finding about the gene and the disease.
tumor (continued). "Moreover, gene markers of Tregs, T cell exhaustion, and MDSCs (myeloid-derived suppressor cells) showed significantly strong positive correlation with DHX37 expression, which gives clues about DHX37 function in modulating tumor immunology in LIHC and LUAD." (PMID 33490290, 2020). "DHX37 is expressed in immune cells and TILs (tumor infiltrating lymphocytes)." (PMID 33490290, 2020). "In addition, we investigated that the expression of DHX37 was correlated with several tumor-related immune genes (PD-L1, TIM3, LAG3, TOX, RGS16, and NCOR2), indicating that it may play crucial roles in tumor immune dysregulation." (PMID 33490273, 2021). "Hence, we analyzed the correlation between DHX37 expression and immunophenotypic characteristics in Pan-Cancer from TIMER and TISIDB (tumor and immune system interaction)." (PMID 33490290, 2020). "In addition, the high expression of DHX37 is found in both activated CD8+ and CD4 T+ cells, and the expression of DHX37 is significantly higher in exhausted tumor infiltration lymphocyte (TILs) compared to nonexhausted ones." (PMID 33490273, 2021).
cancer (6 papers, 2017 to 2025). A tumor composed of atypical neoplastic, often pleomorphic cells that invade other tissues. "In human cancers, nonsense, missense, and synonymous substitution were major types of DHX37 somatic mutations." (PMID 33490273, 2021). "In conclusion, our study is the first to investigate the expression, mutation, and prognostic role of DHX37 in human cancers." (PMID 33490273, 2021). "In the present study, we investigated the expression, mutation, and prognostic role of DHX37 in human cancers, mainly by mining publicly available datasets." (PMID 33490273, 2021). "However, very little is known about the expression, mutation, and prognostic role of DHX37 in human cancers." (PMID 33490273, 2021). "Next, we investigated the somatic mutations of DHX37 in human cancers." (PMID 33490273, 2021). "As far as we know, our study was the first to investigate the prognostic role of DHX37 in human cancers." (PMID 33490273, 2021). "To investigate the prognostic value of DHX37 in human cancers, we used the Kaplan-Meier Plotter to draw the survival curves." (PMID 33490273, 2021). "Our results suggest that DHX37 is upregulated in most human cancers, and it has different prognostic values in various cancers." (PMID 33490273, 2021). "Through biofunctional analysis, we observed that DHX37 was significantly enriched in cancer-related pathways such as cell cycle, DNA replication, mismatch repair, RNA degradation, and RNA polymerase." (PMID 33490273, 2021). "To further reveal the potential relevance of DHX37 expression in cancers, we explored the relationship between DHX37 expression and several clinical features of LIHC and LUAD patients in TCGA cohorts by UALCAN." (PMID 33490290, 2020). "A set of microRNAs was associated with MDSCs and resistance to immunotherapy, which was consistent with our results that show expression of DHX37 induces microRNA in cancer." (PMID 33490290, 2020). "In conclusion, DHX37 can impact cancer prognosis by not only playing direct regulatory roles in cancer cells but also affecting the immune microenvironment." (PMID 33490290, 2020). "Additionally, the presence of functional clusters, such as the interactions among KPNA2, DHX37, and YARS1, indicates possible shared roles in critical cellular processes like RNA processing, which are often implicated in cancer progression." (PMID 39330100, 2024). "To further validate the function of DHX37 in human cancers, we conducted biofunctional analysis." (PMID 33490273, 2021). "The DHX37 expression played different prognostic roles in human cancers." (PMID 33490273, 2021). "In addition, we also observed the protein expression of DHX37 in human cancer cells through the Human Protein Atlas database." (PMID 33490273, 2021). "For survival analysis, DHX37 showed diverse prognostic values in different types of cancers." (PMID 33490273, 2021). "As DHX37 was involved in the regulation of CD8 T cell function, we next checked whether its expression was associated with the expression of some cancer-related immune genes by UCSC Xena." (PMID 33490273, 2021). "In conclusion, the study explored the significance of DHX37 in human cancers." (PMID 33490273, 2021). "In conclusion, our study elucidated the potential role of DHX37 in cancers, and it may serve as a biomarker in some tumors." (PMID 33490273, 2021). "Biofunctional analysis shows that DHX37 is highly enriched in critical cancer signaling pathways." (PMID 33490273, 2021). "Few studies focused on the role of DHX37 in the human immune and cancers." (PMID 33490273, 2021). "We assessed correlations between DHX37 expression and clinical outcomes in 33 types of cancer." (PMID 33490290, 2020).
cancer (continued). "Future prospective studies focusing on these aspects in a comprehensive manner could help identify the function of DHX37 in cancers." (PMID 33490290, 2020). "Interestingly, increased levels of DHX37 expression were related to advanced clinicopathological characteristics, indicating that DHX37 can be used as a prognostic indicator of cancer stages and metastasis." (PMID 33490290, 2020). "This suggests that DHX37 may be a potential biomarker for cancers and is involved in the immune response." (PMID 33490290, 2020). "In research into cancer biology and molecular pathways, we also found DHX37 expression was correlated with metabolic changes including inhibiting fatty acid degradation, amino acid (arginine, histidine valine, leucine, and isoleucine), metabolism, and mitochondrial function." (PMID 33490290, 2020). "Our results substantiate that DHX37 overexpression has far-reaching effects in the immune response and complement systems in cancers, which may ultimately affect patient clinical outcomes." (PMID 33490290, 2020). "Previous immunological characterization of CD8 T cells indicated that DHX37 suppressed effector functions, cytokine production, and T cell activation by modulating NF-κB, which first showed that DHX37 was related to the progression of cancers." (PMID 33490290, 2020). "We explored the prognostic role of DHX37 in cancers across various databases." (PMID 33490290, 2020). "In addition, the expression of DHX37 is correlated with critical inhibitory receptors in cancers." (PMID 33490273, 2021). "DHX37 may serve as a potential target for cancer immunotherapy." (PMID 33490273, 2021). "From the all above, DHX37 might serve as a potential target for cancer immunotherapy." (PMID 33490273, 2021). "Future studies may develop compounds targeting DHX37 for precision medicine in cancers." (PMID 33490290, 2020). "HCC is a common malignant tumor; however, the relationship between DHX37 and HCC has not been comprehensively reported." (PMID 37958405, 2023). "Moreover, DHX37 expression also significantly correlated with CD8 T cells, CD4 T cells, B cells, macrophages, neutrophils, and dendritic cells (DCs) in 16, 19, 12, 18, 16, and 14 types of cancer, respectively." (PMID 33490290, 2020). "However, the intrinsic mechanisms of effects of DHX37 on malignant tumor development and immune regulation have not been investigated." (PMID 33490290, 2020).
neurodevelopmental disorder (4 papers, 2021 to 2024). A behavioral and cognitive disorder with onset during the developmental period that involves impaired or aberrant development of intellectual, motor, or social functions. "Prior to these findings, it was shown that homozygous or compound heterozygous variants in the DHX37 gene were associated with neurodevelopmental disorders characterized by brain abnormalities, as well as potential vertebral or cardiac problems." (PMID 38962685, 2024). "Recent studies have identified variants in DHX37, a gene encoding a putative RNA helicase essential in ribosome biogenesis and previously associated with neurodevelopmental disorders, as a cause of PGD and TRS." (PMID 37240737, 2023). "It is reported to be associated with the neurodevelopmental disorder with brain anomalies, and a recent study suggests that DHX37 is a functional regulator of CD8 T cells." (PMID 33490273, 2021). "Variations of DHX37 are reported to lead to neurodevelopmental disorders and 46,XY DSD." (PMID 38769888, 2024). "There have been reports that homozygous, compound heterozygous, and de novo heterozygous missense variants in DHX37 are associated with neurodevelopmental disorder with brain anomalies and with or without vertebral or cardiac anomalies (NEDBAVC; OMIM# 618731) with an apparent absence of DSD." (PMID 38769888, 2024). "In addition, it was suggested that DHX37 variants associated with DSD may be gain-of-function type, whereas those associated with neurodevelopmental disorder may be loss-of-function variants." (PMID 37240737, 2023).
neurologic disease (2 papers, 2019 to 2025). "As DHX37 has been previously linked to neurologic disease, we found this an especially compelling case of alignment bias producing an appealing but false-positive candidate gene." (PMID 31392989, 2019). "The majority of members of the RNA helicase family have been reported to be associated with neurological diseases, and DHX37 is currently the only helicase gene that is associated with both neurological disorders and DSD, its molecular mechanisms have been reported very little." (PMID 40026690, 2025).
genetic diseases (1 paper, 2025). "The RNA helicase DHX37 gene is involved in ribosomal biological processes, and linked to human genetic diseases associated with 46,XY disorders of sex development (46,XY DSD) or neurodevelopment." (PMID 40026690, 2025). "We searched literature databases and summarized and analyzed all the literature related to DHX37 to date, including case reports, cohort studies, and molecular mechanism studies, to comprehensively demonstrate the role of DHX37 in human genetic diseases." (PMID 40026690, 2025). "This review summarizes the profile of DHX37 defects in human genetic diseases." (PMID 40026690, 2025). "However, there is still a lack of overall understanding of the genetic characteristics, phenotype, etc. of the DHX37 gene in human genetic diseases, and its molecular mechanism is not fully understood." (PMID 40026690, 2025).
DHX37 also shares sentences with these, for which no sentence is quoted: Micropenis (2 papers); pancreatic ductal adenocarcinoma (2); rectum adenocarcinoma (2); sarcoma (2); Skin Cutaneous Melanoma (2); stomach adenocarcinoma (2); uterine corpus endometrial carcinoma (2); bladder carcinoma (1); cervical squamous cell carcinoma (1); colorectal cancer (1); esophageal squamous cell carcinoma (1); Intellectual disability (1); lung carcinoma (1); lymphoma (1); mesothelioma (1); ovarian serous cystadenocarcinoma (1); paraganglioma (1); pheochromocytoma (1); Primary amenorrhea (1); salivary gland carcinoma (1); thymoma (1); triple-negative breast carcinoma (1).